SFRP1 (secreted frizzled related protein 1)
Diseases named in the same sentence as SFRP1 in open-access papers (continued):
Sharing a sentence is not in itself a finding about the gene and the disease.
rheumatoid arthritis (4 papers, 2020 to 2022). A chronic, systemic autoimmune disorder characterized by inflammation in the synovial membranes and articular surfaces. "SFRP1 was reported to function in Th17 cell differentiation and was significantly correlated with IL-17 levels in patients with rheumatoid arthritis." (PMID 35281826, 2022). "As a primitive gene regulating cell growth, development and transformation, SFRP1 is widely expressed in human cells, including various cancer cells and fibroblast-like synoviocytes (FLS) of rheumatoid arthritis (RA)." (PMID 35795672, 2022). "So far, there is no study that directly correlates TNF-α and SFRP-1 with CTX and P1NP, so that this study is expected to provide a better understanding of bone metabolism in patients with rheumatoid arthritis." (PMID 32190056, 2020).
astrocytoma (3 papers, 2018 to 2023). "We also investigated the association of epidemiological characteristics of our astrocytoma samples to SFRP1 methylation status and expression levels of the proteins." (PMID 30394013, 2018). "SFRP1 promoter hypermethylation and the loss of SFRP1 protein expression have been reported in tumorigenesis of many human cancers, but their involvement in astrocytoma progression still needs to be elucidated." (PMID 30394013, 2018). "In a study on astrocytomas of varying degrees of malignancy, the SFRP1 gene was found to be hypermethylated in 32% of samples, and the SFRP1 protein expression was reduced in 45.8% of samples." (PMID 37047705, 2023). "Our previous investigations on SFRP3 in astrocytomas revealed complex expression patterns distinct from the present findings on SFRP1 expression." (PMID 30394013, 2018). "The aim of this study was to identify the status of SFRP1 promoter hypermethylation in different malignancy grades of astrocytoma in order to better understand the molecular features and offer potential biomarkers." (PMID 30394013, 2018). "Malignant astrocytomas of different grades had very different methylation patterns of SFRP1 gene promoter." (PMID 30394013, 2018). "SFRP1 promoter methylation was found in 32% of astrocytomas." (PMID 30394013, 2018). "Although in our total sample there was 45.8% of astrocytomas with weak or lack of SFRP1 protein expression, 25% with moderate, and 29.2% with strong expression, the observed expression values were not significantly assigned to any specific grade." (PMID 30394013, 2018). "Of total astrocytoma samples, 45.8% (11/24) had weak or lack of SFRP1 protein expression, 25% (6/24) had moderate, and 29.2% (7/24) had strong expression." (PMID 30394013, 2018).
cardiomyopathy (3 papers, 2021 to 2024). A disease of the heart muscle or myocardium proper. "Furthermore, treatment of cardiac progenitor cells with sFRP1 promote cellular senescence, and extracellular sFRP1 is associated with doxorubicin-induced cardiomyopathy." (PMID 34383712, 2021). "Although the bulk of this review will focus on the effect of sFRP-1 in cardiomyocytes, sFRP-1 is also important in fibroblast homeostasis, as cardiac fibroblast lacking endogenous sFRP-1 potentially predisposes cells to cardiomyopathy during aging." (PMID 37484982, 2023).
cutaneous squamous cell carcinoma (3 papers, 2017 to 2025). "Previous studies has reported the diagnostic values of SFRP1 methylation in cutaneous squamous cell carcinoma and esophageal squamous cell carcinoma recurrence." (PMID 28422739, 2017). "SFRP1 is the most researched molecule of all the SFRP family proteins, and its tumour suppressor activity has been well established in various types of cancer, such as intrahepatic cholangiocarcinoma and cutaneous squamous cell carcinoma." (PMID 37999144, 2023).
diabetes (3 papers, 2016 to 2022). "Diabetes could induce the expression of Sfrp1 and Sfrp4, but FoxO1 knockout slightly reduced Sfrp1 level." (PMID 33609082, 2021). "In contrast to SFRP1, SFRP3 is negatively related to the occurrence of diabetes." (PMID 35457182, 2022). "The molecular mechanisms of SFRP1, SFRP4, and SFRP5 may have a direct or indirect effect on the development of diabetes." (PMID 35457182, 2022).
esophageal squamous cell carcinoma (3 papers, 2017 to 2023). Esophageal squamous cell carcinoma (ESCC) is a type of esophageal carcinoma (EC) that can affect any part of the esophagus, but is usually located in the upper or middle third. "Furthermore, it has been observed that hypermethylation of certain Wnt inhibitors, namely runt‐related transcription factor 3 (RUNX3), DKK‐3, and sFRP1, is positively associated with the recurrence of esophageal squamous cell carcinoma (ESCC)." (PMID 37901797, 2023). "In esophageal squamous cell carcinoma, DNA methylation and histone acetylation has been found to synergize silencing SFRP1 gene expression." (PMID 28422739, 2017). "SFRP1 promoter hypermethylation has been observed in esophageal squamous cell carcinoma (ESCC) and esophageal adenocarcinoma." (PMID 34640631, 2021).
hepatoblastoma (3 papers, 2020 to 2024). Hepatoblastoma (HB) is a malignant hepatic tumor and is the most common pediatric liver cancer. "Notably, studies have suggested that hypermethylation of the SFRP1 promoter region contributes to transcriptional silencing in hepatoblastoma tumor cell lines." (PMID 38390281, 2024). "Employing chromatin immunoprecipitations (CHIP), one study has suggested that E3 ubiquitin-like containing PHD and RING finger domain 1 (UHRF1) may play a crucial role in the profound silencing of tumor suppressor genes (TSGs) such as HHIP, IGFBP3, and SFRP1 in hepatoblastoma." (PMID 38390281, 2024).
leukemia (3 papers, 2011 to 2021). A malignant (clonal) hematologic disorder, involving hematopoietic stem cells and characterized by the presence of primitive or atypical myeloid or lymphoid cells in the bone marrow and the blood. "Remaining candidates (N = 62) comprised BDNF-related genes (SST), MAPK-pathway genes (KRAS, IGF1R, GNG11 and RAP1A), genes related with leukemia (SFRP1) and Rho-Proteins (DHCR7 and RAB21)." (PMID 21569303, 2011).
liver fibrosis (3 papers, 2020 to 2026). "In addition, siRNA-mediated inhibition of Sfrp1 expression remarkably increased intra-nuclear β-catenin level, and consequently caused hepatic fibrosis." (PMID 32232014, 2020). "It was reported that SFRP1 can inhibit Wnt signaling pathway, which was involved in promoting hepatic fibrosis by enhancing HSCs activation and survival." (PMID 32232014, 2020). "SFRP5 appears to function similarly to SFRP1 in liver fibrosis." (PMID 41541657, 2026).
lymph node metastasis (3 papers, 2018 to 2020). "In addition, 49.5% (54/109) patients with low SFRP1 level correlated with advanced tumor stage (P = 0.007) and lymph node metastasis (P = 0.010)." (PMID 30158579, 2018). "Bartak discovered that the SFRP1 methylation was not connected with lymph node metastasis." (PMID 31830937, 2019).
medulloblastoma (3 papers, 2014 to 2023). A malignant, invasive embryonal neoplasm arising from the cerebellum. "Three SFRP members including SFRP1 can reduce Wnt signaling and thus impede proliferative activity and anchorage‐independent growth of medulloblastoma cells; meanwhile, SFRP1 curbs in vivo formation of medulloblastoma." (PMID 36756719, 2023).
mucoepidermoid carcinoma (3 papers, 2015 to 2023). A carcinoma morphologically characterized the presence of cuboidal mucous cells, goblet-like mucous cells, squamoid cells, cystic changes, and a fibrotic stromal formation. "Conversely, in mucoepidermoid carcinoma samples, a lower concentration of SFRP1 was associated with high-grade tumours." (PMID 37999144, 2023). "Loss of SFRP1 expression was associated with aberrant β-catenin distribution and tumor progression in mucoepidermoid carcinoma of salivary glands." (PMID 27534621, 2016).
nasopharyngeal carcinoma (3 papers, 2018 to 2025). A carcinoma arising from the nasopharyngeal epithelium. "However, some studies have demonstrated that, in nasopharyngeal carcinoma, patients with low expression of SFRP1 exhibited significantly worse OS, DFS rate, and distant metastasis-free survival compared to patients with high expression of SFRP1." (PMID 39729237, 2025). "Furthermore, we found that Wnt5B, SFRP1, and SFRP2 were hypermethylated in nasopharyngeal carcinoma tissues, and the hypermethylation of DKKs and DACTs in nasopharyngeal carcinoma tissues was also confirmed." (PMID 30075814, 2018).
polyp (3 papers, 2008 to 2016). A usually exophytic mass attached to the underlying tissue by a broad base or a thin stalk. "This is consistent with observations showing a positive association between RCF and methylation of SFRP1 and ESR1 in the apparently normal mucosa of previous polyp patients." (PMID 23157586, 2013).
Renal clear cell carcinoma (3 papers, 2021 to 2023). "In renal clear cell carcinoma, promoter hypermethylation of SFRP1 has been associated with poor survival and outperforms tumor stage, tumor grade, and tumor size as an independent survival marker." (PMID 34830873, 2021). "Renal clear cell carcinoma-derived miR-27a-loaded exosomes inhibit secreted frizzled-related protein 1 (SFRP1) expression and accelerate tumor angiogenesis." (PMID 34211501, 2021).
renal fibrosis (3 papers, 2020 to 2026). A final common manifestation of a wide variety of chronic kidney diseases characterized by glomerulosclerosis and tubulointerstitial fibrosis. "However, the associations of miR-27a, Sfrp1, Wnt/β-catenin signalling, and renal fibrosis remain undefined." (PMID 32484208, 2020). "We concluded that miR-27a down-regulated Sfrp1 and activated Wnt/β-catenin signalling to promote renal fibrosis." (PMID 32484208, 2020). "In conclusion, we found that miR-27a activates Wnt/β-catenin signalling by down-regulating Sfrp1, thus promoting the occurrence of renal fibrosis." (PMID 32484208, 2020). "Conversely, si-Sfrp1 promoted the development of renal fibrosis, which was alleviated in the si-Sfrp1+miR-27a inhibitor co-transfection group." (PMID 32484208, 2020). "These seemingly contradictory findings may arise from differences in experimental models, underscoring the need for further investigation into SFRP1's role in renal fibrosis." (PMID 41541657, 2026). "Therefore, Sfrp1 acts as a negative regulator of the Wnt signaling pathway and suppresses renal fibrosis via inhibiting the Wnt/β-catenin signaling pathway." (PMID 34483931, 2021). "This work aimed to investigate whether miR-27a can promote the occurrence of renal fibrosis in DN by suppressing the expression of secreted frizzled-related protein 1 (Sfrp1) to activate Wnt/β-catenin signalling." (PMID 32484208, 2020). "The results showed that transfection with si-Sfrp1 induced Wnt/β-catenin signalling pathway, increased ECM deposition, and promoted the development of renal fibrosis, whereas co-transfection with miR-27a inhibitor attenuated these effects." (PMID 32484208, 2020). "SFRP1 and SFRP5 play pivotal roles in renal fibrosis, though their mechanisms remain complex." (PMID 41541657, 2026). "Additionally, down-regulation of Sfrp1 activates the Wnt/β-catenin signaling pathway, increased ECM deposition, eventually lead to renal fibrosis." (PMID 34483931, 2021).
tuberculosis (3 papers, 2014 to 2016). A chronic, recurrent infection caused by the bacterium Mycobacterium tuberculosis. "Previous investigations have revealed the associations of genetic variants in the SFRP1 gene with tuberculosis, inflammation, and cancer susceptibility." (PMID 27391264, 2016). "Five polymorphisms were associated with tuberculosis susceptibility after Bonferroni correction: SFRP1 rs4736958, CTNNB1 rs9859392, rs9870255 and rs3864004 showed decreased tuberculosis risk; SFRP1 rs7832767 was related to an increased risk (OR = 1.81, 95% CI = 1.30–2.52, p = 0.010)." (PMID 27334567, 2016). "Individuals with TT genotype were more likely to be infected with TB, indicating SFRP1 may be a candidate gene for tuberculosis determinant." (PMID 24695522, 2014).
ampullary adenocarcinoma (2 papers, 2020 to 2024). "SFRP1 mRNA expression in ampullary adenocarcinoma was lower than in other periampullary adenocarcinomas; however, there was a trend of higher SFRP1 mRNA in ampullary adenocarcinoma patients with recurrence." (PMID 32764696, 2020). "High SFRP1 expression was correlated with poor prognosis, early recurrence and peritoneal carcinomatosis of ampullary adenocarcinoma patients." (PMID 32764696, 2020). "The expression level of SFRP1 mRNA was similar in patients with a recurrence of ampullary adenocarcinoma (median log2 ratio of SFRP1, 7.24; range, 7.02–8.55) and in patients without recurrence (median log2 ratio of SFRP1, 7.21; range, 7.02–8.55)." (PMID 32764696, 2020). "Monoclonal anti-SFRP1 antibody is a potential drug for cancers with malignant SFRP1 networks, including gastric and ampullary adenocarcinoma." (PMID 32764696, 2020). "We employed immunohistochemistry (IHC) staining to detect the expression of SFRP1 protein in cancer samples to verify the impact of SFRP1 on the survival of ampullary adenocarcinoma patients." (PMID 32764696, 2020). "The IHC results indicated that the influence of SFRP1 expression in survival of ampullary adenocarcinoma patients was similar to rectal and gastric adenocarcinomas." (PMID 32764696, 2020). "Then, we studied protein and mRNA expression in clinical samples from patients with ampullary adenocarcinoma to verify the function of SFRP1 in ampullary adenocarcinoma." (PMID 32764696, 2020). "We collected samples from all subtypes of ampullary adenocarcinoma and elucidated the function of SFRP1." (PMID 32764696, 2020). "Gene set enrichment analysis showed downregulation of multiple WNT-related genes in primary culture cells from ampullary adenocarcinoma, but SFRP1 expression was increased." (PMID 32764696, 2020). "In patients with ampullary adenocarcinoma, the expression level of SFRP1 is lower than other periampullary adenocarcinomas." (PMID 32764696, 2020). "Understanding SFRP1 expression phenotype in ampullary adenocarcinoma will help in the development of new therapeutic agents." (PMID 32764696, 2020). "The expression of SFRP1 mRNA in the UTMDACC dataset was higher in ampullary adenocarcinoma patients with recurrence, especially in those with pancreaticobiliary subtypes." (PMID 32764696, 2020). "Because it is a multifunctional protein, SFRP1 targeting serves as a potential therapy for ampullary adenocarcinoma patients." (PMID 32764696, 2020). "SFRP1 expression in ampullary adenocarcinoma was detected by immunohistochemistry staining and correlated with patients’ clinical outcomes." (PMID 32764696, 2020). "Furthermore, a high expression of SFRP1 predicted poor prognosis for ampullary adenocarcinoma patients." (PMID 32764696, 2020). "However, high expression of SFRP1 is correlated with poor prognosis of patients with ampullary adenocarcinoma in our present study." (PMID 32764696, 2020). "We employed IHC staining to study SFRP1 expression in ampullary adenocarcinoma." (PMID 32764696, 2020). "Therefore, WNT-associated signalling required consideration to explain the function of SFRP1 in ampullary adenocarcinoma." (PMID 32764696, 2020). "Additionally, we performed IHC staining to verify expression of SFRP1 protein in ampullary adenocarcinoma." (PMID 32764696, 2020). "No detected alteration of SFPR1 gene and SFRP1 expression in ampullary adenocarcinoma was lower than that in other periampullary adenocarcinomas." (PMID 32764696, 2020). "In ampullary adenocarcinoma, there was no alteration of SFRP1 in DNA sequencing or in copy number." (PMID 32764696, 2020).
Arthritis (2 papers, 2018 to 2024). Inflammation of a joint. "The third Wnt inhibitor investigated, SFRP1, was highly expressed only after arthritis onset in the AIA model." (PMID 29472591, 2018). "The low osteoblast activity correlated with sclerostin in early arthritis and SFRP1 in established arthritis." (PMID 29472591, 2018). "At the ankle level, higher sclerostin concentration was observed at the protein level in the AIA group compared to CTRL group from day 6 to 10 (p < 0.05), while SFRP1 protein expression was only enhanced after arthritis onset (p < 0.01)." (PMID 29472591, 2018). "We demonstrated that DKK1 and sclerostin were only upregulated before arthritis onset, while SFRP1 was only upregulated after arthritis onset." (PMID 29472591, 2018). "Taken together, these results suggested that inhibition of bone formation was more likely to be explained by SOST in early arthritis and by SFRP1 in late arthritis, suggesting a switch in the role of Wnt inhibitors." (PMID 29472591, 2018). "Contrarily, SFRP1 was higher in AIA compared to CTRL only after arthritis onset (p < 0.01)." (PMID 29472591, 2018). "At the time of arthritis onset, SOST and DKK1 returned to control values, but frizzled related protein 1 (SFRP1), proinflammatory cytokines, and MMPs started to increase." (PMID 29472591, 2018). "Our data with up regulation of SFRP1 after arthritis onset are not consistent with previous data from human samples." (PMID 29472591, 2018). "Before arthritis onset at day 8, OS/BS was inversely correlated with SOST (r = −1, p < 0.02) but not with DKK1 or SFRP1 (r = −0.50, p = 0.45 for both), suggesting that high SOST at day 8 correlated with low osteoblast activity." (PMID 29472591, 2018).
biliary tract cancer (2 papers, 2014 to 2015). "Inverse correlation between SFRP1 expression and β-catenin expression in human biliary tract cancer*." (PMID 24594839, 2014). "Relationships between the expression of SFRP1, β-catenin and clinicopathologic features in human biliary tract cancer." (PMID 24594839, 2014). "Immunohistochemical Staining of SFRP1 and β-catenin expression in human biliary tract cancer versus normal bile duct tissues." (PMID 24594839, 2014). "We sought to determine whether the expression of SFRP1 and β-catenin correlates with clinicopathologic parameters in human biliary tract cancer (BTC) and to evaluate the potential roles of these proteins as prognostic indicators." (PMID 24594839, 2014).
bladder urothelial carcinoma (2 papers, 2015 to 2022). "Moreover, we observed that both the SFRP1 and SFRP2 transcripts are significantly negatively correlated with tumor purity and positively correlated with CAF infiltration in bladder urothelial carcinoma, but the SFRP2 gene showed a more distinguished correlation." (PMID 35372028, 2022).
diabetic nephropathy (2 papers, 2020 to 2023). "We searched the literature for the first five genes and discovered that the expression of secreted frizzled-related protein 1 (SFRP1) was associated with multiple kidney diseases, including renal cell carcinoma, obstructive nephropathy, and diabetic nephropathy." (PMID 37588659, 2023). "The studies have confirmed that there was a certain correlation between SFRP1 and the formation of renal interstitial fibrosis, and it was speculated that SFRP1 exerted a critical role in the pathogenesis and development of diabetic nephropathy." (PMID 37588659, 2023).